USP9X (ubiquitin specific peptidase 9 X-linked)
Diseases named in the same sentence as USP9X in open-access papers (continued):
Sharing a sentence is not in itself a finding about the gene and the disease.
cancer (continued). "As it has been proven that substrates for Degrasyn (e.g., USP9X) might regulate the Bcl-2 family axis, their inhibition may contribute to the anti-cancer effect of Degrasyn." (PMID 36979739, 2023). "Not only is the regulation of various genes by USP9X a complex and dynamic process important for the occurrence and development of cancer, there may also be more than one downstream target of USP9X." (PMID 37057289, 2023). "An increasing number of studies have shown that USP9X is closely related to cancer." (PMID 37057289, 2023). "USP9X dysfunction contributes to neurological diseases and cancers." (PMID 35389885, 2022). "Consequently, USP9X processes function of both oncogene and tumor suppressor, depending on the type and stage of cancer." (PMID 34112167, 2021). "Several DUBs, including USP9X, are frequently dysregulated in cancers." (PMID 34112167, 2021). "Indeed, although not represented on either of the curated CGC or TSGdb lists, several genes (e.g., Cep350, Ncoa2, and Usp9x) have all been observed in other SB tumor screens and experimentally validated to be TSGs within mouse models and/or human cancer cells." (PMID 33435458, 2021). "In some cancers, USP9X has been shown to modulate chemoresistance." (PMID 34856948, 2021). "Through a ubiquitin-specific protease activity, USP9X not only plays a paramount role in regulating the proliferation, apoptosis, and adhesion of cancer cells, but also maintains the stability of DNA replication-fork and DNA-damage checkpoint responses, thus affecting radiosensitivity." (PMID 32850399, 2020). "Moreover, IITZ-01 upregulated DR5 and downregulated Cbl, USP9X and survivin in all examined cancer cells." (PMID 32825566, 2020). "Moreover, targeting respective phosphatase/kinase–DUB interactions would be an attractive approach to inhibit singular oncogenic activities of USP9X in the context of cancer treatment." (PMID 32152317, 2020). "Additional studies to determine key components in the apoptotic pathway and a role for USP9X in this process may help develop more effective cancer therapies." (PMID 32354135, 2020). "Moreover, knockdown of USP9X enhances the sensitivity of human cancer cells to PARP inhibitor Olaparib and MMS." (PMID 31512408, 2019). "Our results provide a rationale to develop a USP9X-IRS-2 binding inhibitor as a cancer therapy." (PMID 30338032, 2018). "Loss of USP9X causes chromosomal instability (CIN), which can promote cancer." (PMID 29669289, 2018). "However, mechanistic insights into the role of USP9X in cancer development and progression remain to be investigated." (PMID 28361952, 2017). "In addition to targeting the Hippo pathway via regulation of AMOT, several other cancer-relevant targets have been reported for the USP9x deubiquitylase." (PMID 27462448, 2016). "Recent literature on the role of USP9x in cancer is equivocal." (PMID 27462448, 2016). "In addition to gene expression changes, exome sequencing and recurrence testing show that USP9X is frequently altered in many cancers." (PMID 25672900, 2015). "From a mechanistic point of view, we identified down-regulation of Usp9X as well as Bag3 followed by enhanced Mcl-1-degradation as one of the driving mechanisms subjacent to the profound anti-cancer activity inherent to a combined inhibition of ERK signaling and Bcl-2/Bcl-xL." (PMID 26474387, 2015). "Together, these (and other) studies reveal that USP9X expression is deregulated in cancers." (PMID 25672900, 2015). "Thus in multiple cancer cell types, the level at which USP9X is able to deubiquitylate and stabilise MCL1 dictates its anti-apoptotic function." (PMID 25672900, 2015). "Usp9X modulates Mcl-1 levels and counteracts apoptosis in cancer cells." (PMID 26008975, 2015). "Recent evidence indicates that USP9X is involved in the progression of various human cancers." (PMID 24152793, 2013).
cancer (continued). "Hence, we suspect that the roles of USP9X in cancer are likely to be complex and context-dependent, similar to what has been observed for TGFβ." (PMID 23667531, 2013). "The impact of these studies is likely to have implications for the role of USP9X in other cancers." (PMID 23667531, 2013). "To determine the impact of USP9X inhibition on cancer cell survival in our present experiments, we used its inhibitor WP1130 and found that the treated cells showed Mcl-1 downregulation which increased their sensitivity to ABT-737 as well as to other chemotherapeutic agents." (PMID 23171055, 2012). "Furthermore, our analyses revealed that USP9X expression correlates with that of Mcl-1 in human cancer tissue samples." (PMID 23171055, 2012). "Our current research suggests that USP9X regulates Mcl-1 expression in cancer cells." (PMID 23171055, 2012). "USP9X might also act as a regulator of the TGF-β pathway, another signaling circuitry of great relevance to cancer, as witnessed by the fact that loss of USP9X abolishes multiple TGF-β gene responses." (PMID 21283576, 2011). "USP9X has a complex role in cancer, with both pro- and anti-tumourigenic functions and this may be related to the fact that it not only regulates Hippo signalling, but also other pathways such as TGF-β, Wnt and JAK-STAT, both in mammals, as well as in Drosophila35." (PMID 39994229, 2025). "These experiments suggest that USP9X could be a therapeutic target for various cancers." (PMID 34405018, 2021). "Interestingly, USP9X exerts different functions in different cancers." (PMID 34405018, 2021). "Thus, targeting PD-L1 by blocking USP9X may be a potentially useful strategy in the treatment of cancer cells." (PMID 32850399, 2020). "Similarly to other cancers, contrasting evidence on the role of USP9x in SCCs has been reported." (PMID 32560247, 2020). "As it has been shown that treatment with PARP inhibitor Olaparib enables to induce BRCA1 foci formation in human cancer cells, we next examined whether depletion of USP9X could affect Olaparib induced the formation of BRCA1 foci using immunofluorescent staining." (PMID 31512408, 2019). "Importantly, reduced USP9X expression predicted poor survival in human cancers." (PMID 29346117, 2018). "Interestingly, USP9X has been found overexpressed in some other human cancers, such as non-small cell lung cancer, multiple myeloma, and squamous cell carcinoma, implying that in different contexts, it also may act as an oncogene." (PMID 29673168, 2018). "Furthermore, we re-introduced the USP9X siRNA into the miR-26b inhibbited HCC cancer cells." (PMID 24890815, 2014). "Using proteomics and ubiquitinomics, we show that USP9X targets distinct substrates compared to USP7, yet the substrate profile of USP9X varies significantly across cancer cell lines." (PMID 41946992, 2026). "USP9X, as a DUB, functions in promoting stemness of CSCs and contributes to the radioresistance/chemoresistance of several types of cancers, mainly by deubiquitylating different substrates." (PMID 40246814, 2025). "Suppression of USP9X in OSCC has emerged as a potential strategy to inhibit tumor growth, suggesting that USP9X is a potential therapeutic target for this cancer type." (PMID 38474186, 2024). "At least five DUBs were reported to stabilize PD-L1 in different cancers, including USP7, USP9X, USP22, CSN5 and OTUB123,37–40." (PMID 38167274, 2024). "Given that USP9x depletion significantly affected metabolism in NSCLC cells, warrants this DUB as an important regulator of cancer metabolism." (PMID 39075050, 2024). "Many USPs, including USP2, USP7, USP10, USP22, USP44, and USP9X, have been extensively studied about their role in different types of cancer, which has led to the development of inhibitors for USP1, USP7, USP9X, and USP14." (PMID 37118828, 2023).
cancer (continued). "Studies have shown that USPs (USP2a, USP4, USP9X, USP15, and USP26) are involved in the regulation of TGF-β signaling pathways in various cancers." (PMID 35924159, 2022). "USP9X was first found to regulate YAP via direct or indirect mechanisms as a DUB of AMOTL2, LATS, or YAP in different cancers." (PMID 34055773, 2021). "WP1130 is a DUB inhibitor with some selectivity for USP9X that was shown to reduce MCL-1 and induce cancer cell apoptosis, as well as reduce chemoresistance in various tumor types." (PMID 34203106, 2021). "In the last decade, elucidating the role of many USPs, such as USP2, USP7, USP10, USP22, USP44, USP9X, and USP14, in different cancers led to the development of inhibitors for USP7, USP14, USP1, and USP9X." (PMID 34758854, 2021). "E3 ubiquitin ligases (Mule, SCFβ-TrCP, SCFFBW7, TRIM17, APC/CCdc20, and FBXO4) and deubiquitinases (USP9X, Ku70, USP13, JOSD1, and DUB3) work together to balance MCL1 stability, which has an important role in the chemoresistance of cancer cells." (PMID 33803505, 2021). "IITZ-01 induced Cbl-mediated DR5 stabilization and USP9X-dependent survivin degradation, resulted in the enhancement to TRAIL sensitivity in cancer." (PMID 32825566, 2020). "Of note, USP9X (log2FC/FDR = −0.31/1.7e-06), a previously reported cancer driver, TXLNG (−0.54/3.3e-17), OFD1, MED14, and CDK16 are known to evade X-inactivation and were over-expressed in females’ GC." (PMID 32849808, 2020). "The anti-cancer effects of WP1130 rely primarily on the inhibition of USP9X, and inhibition of USP9X by WP1130 induces downregulation of Mcl-1 and XIAP expression." (PMID 30862047, 2019). "To understand the molecular mechanism of FBW7 regulation in these cancers, we employed proteomics and identified the deubiquitinase (DUB) USP9X as an FBW7 interactor." (PMID 29346117, 2018). "We then directly investigated the relationship between RBBP6, USP9X, ZBTB38, and CDKN1C expression and the clinical response to azacytidine in cancer patients." (PMID 30310057, 2018). "WP1130 can also inhibit the deubiquitinase activity of USP9X, and treatment with WP1130 can promote apoptosis by decreasing the level of MCL-1 and increasing the sensitivity of cancer cells to traditional chemotherapy." (PMID 30319415, 2018). "USP9X, also referred to as FAM, is a substrate-specific DUB, which plays pivotal roles in human cancers, both as an oncogene or as a tumor suppressor." (PMID 30319415, 2018). "Many cancer cells have increased levels of Mcl-1 protein due to the misregulation of cellular UPS factors like MULE, USP9X and components of the SCFFbw7 complex which promotes apoptosis resistance." (PMID 28347402, 2017). "Using the USP9X inhibitor CP2005, we successfully rescued pVHL levels and decreased growth rate of cancer cells both with wild type and with mutant pVHL." (PMID 27517496, 2016). "USPs, such as USP1, USP2, USP7, USP9x and USP14, were recently shown to contribute to the development of cancer and are emerging as novel cancer drug targets." (PMID 27780924, 2016). "In this study, we present that USP9x interacts with the PYCR3 enzyme, promoting its stability through deubiquitination-mediated regulation, thus revealing a previously uncovered role of this DUB as a direct regulator of proline metabolism in cancer cells." (PMID 39075050, 2024). "Our observations that USP9X interacts with and deubiquitinates MTH1 in HGC-27 cells and controls the proliferation, survival, migration, and invasion of GC cells expand our knowledge about the function and target of USP9X in cancer biology." (PMID 39075342, 2024). "In addition, USP8, USP15, USP9X and USP18 are also being reported by a growing number of top research institutes for their vital immunomodulatory functions in cancer progression." (PMID 37658402, 2023).
cancer (continued). "As Degrasyn (a selective inhibitor of USP5, USP9X, and USP14) has shown an inhibitory effect on some cancer types, our aim was to determine whether Degrasyn could be a potential therapeutic agent in BC." (PMID 36979739, 2023). "Tobacco related genes, such as USP9X, ARID2, MLL4, TRPM3 and UNC13C, exactly showed no mutations in buccal mucosal cancer cell lines with no risk-habits of tobacco smoking or chewing." (PMID 36611830, 2022). "Other Usp9x substrates in cancer (e.g., Ets-1, MCL-1) may also contribute to the anti-tumor activity of Usp9x inhibition and warrants further assessment." (PMID 33613844, 2021). "In fact, a role for USP9X in cancer development is not yet clear, having been found to act both as an oncogene and a tumor suppressor, depending on the type and stage of cancer." (PMID 34277417, 2021). "Usp9x deubiquitinates proteins essential in cancer cell signaling and survival, as non-ubiquinated proteins are not targeted for degradation by the proteasome." (PMID 33613844, 2021). "Several E3 ligase (Cullin3-SPOP, c‐Cbl, and β-TrCP) and deubiquitinases (CSN5, USP9X, USP21, OTUB1, and USP22) have been reported to regulate PD-L1 protein degradation in cancer cells, indicating posttranslational modification plays an important roles in regulation of PD-L1 stability." (PMID 34741014, 2021). "These USP9X functions are similar to those of USP44, implying that USP9X might be a potential therapeutic target in the treatment of various cancers." (PMID 31795161, 2019). "Consequently, USP9X regulates BRCA1‐mediated HR repair and confers resistance to DNA‐damaging agents in human cancer cells." (PMID 31512408, 2019). "Moreover, USP9X regulates BRCA1‐mediated HR repair and promotes resistance of cancer cells to DNA‐damaging agents." (PMID 31512408, 2019). "Reduced USP9X strongly correlates with reduced FBW7 protein and poor prognosis in human cancers." (PMID 29346117, 2018). "DUBs are critical key players in diverse processes such as (i) spermatogenesis (e.g. USP2, USP8, USP9y, USP14, USP26, Uchl-1, Uchl-3 and CYLD), (ii) cancer biology (e.g. USP7, USP10 and USP11), and (iii) stemness and differentiation (e.g. USP7, USP9x, USP22, USP44 and Psmd14)." (PMID 28659380, 2017). "For instance, USP9x, a deubiquitinase, and connected with CTNNB1 as shown in the network, has been reported to be required for PKCβ kinase activity and induced the cell survival and tumor-promoting activities of Notch signaling in cancer." (PMID 28054945, 2017). "Moreover, we have identified an edge relating the genes with transmembrane protein function with those from the spliceosome (U2AF1, and USP9X) and the cohesin complex (SMC1A and STAG2) that have an important role in cancer." (PMID 26886259, 2016). "Finally, while 15 DUBs were found to be significantly dysregulated in only one type of cancer, 7 (UCHL1, USP9X, USP11, USP10, USP22, COPS5 and COPS6) displayed multiple alterations in two or more tumor types." (PMID 21283576, 2011). "Similar as previously reported, HIF-2α may account for the chemoresistance, since reduction of HIF-2α positive proportion of CSCs occurred simultaneously with regained cell apoptosis so as to sensitivities to chemotherapeutic drugs within USP9X-knockdown CDDP and PTX-resistant cancer cells." (PMID 40246814, 2025). "In addition, ubiquitin-specific peptidase 9 X-linked (USP9X) was shown to regulate the canonical and noncanonical Wnt pathways in cancer development via the deubiquitylation of DVL257." (PMID 37524878, 2023). "We hypothesized that Usp9x and SOX2 axis may play a broader role in other cancers." (PMID 33613844, 2021). "In addition, unbiased determination of USP9X targets and its regulation may yield a more comprehensive assessment of DUB activity in cancer cells." (PMID 32354135, 2020).
cancer (continued). "In view of our results, and considering the fact USP9X targets a variety of substrates, we propose that downregulation of the pVHL-HIF pathway resulting in promotion of cell proliferation is one mechanism by which the activity of USP9X promotes cancer progression." (PMID 27517496, 2016). "In addition it has been reported that USP9X influences cell apoptosis by stabilizing MCL-1, but the USP9X substrate that takes part in regulation of cell proliferation and cancer progression had not heretofore been identified." (PMID 27517496, 2016). "In the present study, we investigated USP9X expression and its potential clinical significance in normal esophageal epithelium, ESCC and its precursor lesions, trying to clarify the possible function of USP9X in the cancer malignancy, progression and prognosis." (PMID 24152793, 2013). "However, to the best of our knowledge, no targeted agents against UBE2T, UBE2C, BIRC5, or USP9X, either approved or in development, can be found in The Drug Gene Interaction Database or Genomics of Drug Sensitivity in Cancer database, while the only USP7 inhibitor, P22077, has not been tested in BC." (PMID 33671201, 2021).